PYY (peptide YY)
Diseases named in the same sentence as PYY in open-access papers (continued):
Sharing a sentence is not in itself a finding about the gene and the disease.
irritable bowel syndrome (9 papers, 2013 to 2025). Irritable bowel syndrome (IBS) is a chronic functional condition of the lower gastrointestinal (GI) tract characterized by abdominal pain or discomfort and disordered bowel habit (diarrhea, constipation, or fluctuation between the two). "PYY increases satiety, reduces food intake, delays gastric emptying, and regulates energy expenditure, and has been associated with several GI diseases, including irritable bowel syndrome, inflammatory bowel disease, celiac disease, and diabetic gastroenteropathy." (PMID 26506614, 2015). "In patients with irritable bowel syndrome, PYY concentration and PYY cell count are reduced in the colon, indicating abnormalities in PYY related to irritable bowel syndrome pathology." (PMID 40075879, 2025). "For instance, the density of PYY cells in the colon is lower in patients suffering from CD and irritable bowel syndrome." (PMID 35443853, 2022). "Abnormalities in PYY seem to contribute to the development ofsymptoms present in irritable bowel syndrome, inflammatory bowel disease,gastroenteropathy in long-standing diabetes and CST." (PMID 23292145, 2013). "Interestingly, PYY-cell density is also increased in patients with irritable bowel syndrome with constipation." (PMID 41131424, 2025). "Irritable bowel syndrome may cause hemorrhoid and peptide YY plays an important role in the pathophysiology of irritable bowel syndrome." (PMID 33664665, 2020). "Previous studies on irritable bowel syndrome (IBS) suggest that low PYY concentration and a low density of PYY cells in the large intestine contribute to dysmotility and visceral sensitivity observed in IBS patients." (PMID 40142315, 2025).
colitis (8 papers, 2013 to 2025). Inflammation of the colon. "Subsequently, in the DSS-induced colitis model, we found that intraperitoneal injection of PYY alleviates weight loss and results in a longer colon length." (PMID 40340969, 2025). "A very recent study showed PYY deficiency in mice disturbed the gut microbiome composition in response to a high-fat diet, indicating PYY 3–36 and gut microbiota might have potential correlation in colitis." (PMID 35443853, 2022). "In mouse colonic mucosa, PYY-positive cell numbers significantly decreased during the injury phase of radiation-induced colitis but recovered during the repair phase." (PMID 40340969, 2025). "While it exerts beneficial effects on metabolic health through mechanisms such as bacterial fermentation metabolites that stimulate intestinal GLP-1 and PYY secretion, it can also exacerbate intestinal inflammation in colitis." (PMID 41133791, 2025). "Our observations indicate alterations in the expression of certain SCFA receptors and the hormone PYY in colitis, while the expression of SCFA transporters remained unchanged." (PMID 38595917, 2024). "To examine the possible role of PYY in IBD, we initially detected the expression of PYY and PYY receptors in the colon mucosae of mice with CD-like colitis induced by trinitrobenzene sulfonic acid (TNBS)." (PMID 35443853, 2022). "In our finding, PYY 3–36 strongly mitigated the loss of body weight, colonic inflammation, and MPO activity and increased the survival rate in mice with TNBS-induced colitis." (PMID 35443853, 2022). "In a wider perspective, these findings point to a potential involvement of PYY in the pain and emotional-affective alterations seen in animal models of colitis and IBD patients alike." (PMID 29213271, 2017). "Considering the decreased intestinal NPY and PYY levels in cpe−/− mice, we next analyzed colonic cytokine transcript levels of both genotypes at baseline conditions and after experimental colitis induction via quantitative RT-PCR." (PMID 25051500, 2014). "Additionally, PYY improved intrinsic defects in the intestinal epithelium of clinical colitis specimens, further supporting its potential as a therapeutic strategy for colonic mucosal repair." (PMID 40340969, 2025). "Analysis of specimens from chronic radiation-induced colitis and control colonoscopy biopsies showed that PYY expression, predominantly located in the upper part of normal crypts, diminished significantly in chronic radiation-induced colitis, correlating with the severity of colonic mucosal damage." (PMID 40340969, 2025). "To determine whether PYY was involved in gastrointestinal injury, we initially established a CD-like mouse model in which colitis was induced by TNBS." (PMID 35443853, 2022). "Guided by these findings, we hypothesized that PYY plays functional roles in the pathogenesis of colitis." (PMID 35443853, 2022). "This suggests that not only PYY, but also Y1, Y2, and Y4, participate in experimental colitis." (PMID 35443853, 2022). "In addition, PYY protein level in mice with TNBS-induced colitis was significantly higher than the other two groups." (PMID 35443853, 2022). "Additionally, the other two peptides from same family, neuropeptide Y (NPY) and pancreatic polypeptide, bind to the same receptors as PYY and may also play some unknown functional roles in the experimental colitis mouse model." (PMID 35443853, 2022). "Therefore, we established and utilized the TNBS-induced colitis CD-like mouse model to address whether PYY is involved in CD and determine its potential role CD." (PMID 35443853, 2022). "Further studies uncovered that PYY 3–36 treatment reduced the levels of colon myeloperoxidase (MPO) and both colonic and systemic TNF-α and IL-6 observed in murine colitis." (PMID 35443853, 2022). "The results showed that the expression of colonic mucosal PYY and PYY receptors Y1, Y2, Y4 were significantly increased in mice with TNBS-induced colitis." (PMID 35443853, 2022).
Hyperinsulinemia (7 papers, 2008 to 2025). An increased concentration of insulin in the blood. "In aged mice, besides high plasma PYY levels, abnormality of many feeding-related factors such as hyperghrelinemia, hyperleptinemia, hyperinsulinemia is exhibited under freely fed condition." (PMID 29129830, 2017). "In this situation, nutritional deficiency occurs with early stimulation of the distal gut, increased secretion of GLP- 1 and PYY, and hyperinsulinemia and intestinal hypermotility." (PMID 27683787, 2016). "Interestingly, levels of several hormonal peptides related to hyperinsulinemia, such as insulin, leptin, pancreatic peptide (PP), peptide YY (PYY), and gastric inhibitory polypeptide (GIP), were significantly upregulated." (PMID 39851552, 2025). "Anastomosing food loop with the pre-pyloric antrum restores normal intestinal tract and entero-insular axis, resulting in PYY and GLP 1 decrease and, consequently, intestinal hypermotility and hyperinsulinemia." (PMID 27683787, 2016). "PYY reinforces the insulin action on glucose disposal in muscle and adipose tissue and GLP-1 increases peripheral glucose-mediated glucose uptake independently of hyperinsulinemia." (PMID 26292284, 2015). "Whether hyperinsulinemia contributes to this phenotype is not agreed but tonic inhibition afforded by PYY acting on Y1 receptors in pancreatic islets combined with Y2 inhibition of vagal output have been proposed as coincident contributing factors." (PMID 18662856, 2008).
inflammatory bowel disease (7 papers, 2012 to 2025). A spectrum of small and large bowel inflammatory diseases of unknown etiology. "Intestinal NPY, PYY, and PP are reported to be abnormal in patients with inflammatory bowel disease and its animal models with increased plasma IL-6." (PMID 29429048, 2018). "These abnormalities in PYY seem to contribute to the development of symptomsseen in gastrointestinal diseases/disorders such as gastroenteropathy in long-standingdiabetes, inflammatory bowel disease and CST." (PMID 23292145, 2013). "Given that IBS and inflammatory bowel disease (IBD) are associated with pain, we hypothesized that a deficiency in PYY contributes to the hyperalgesia associated with these pathologies." (PMID 28106168, 2017). "PYY may have a role in the pathogenesis of a number of anorectic conditions such as inflammatory bowel disease, steatorrhea, tropical sprue, and cardiac cachexia, since plasma PYY levels are elevated in patients with these conditions." (PMID 22899902, 2012). "However, PYY is predominantly secreted by intestinal L cells located in the distal gastrointestinal tract, and it has been reported that the PYY levels are decreased in patients with inflammatory bowel disease." (PMID 24675731, 2014).
colon carcinoma (6 papers, 2005 to 2023). "HCT116 and Caco2 colon cancer lines increased Bcl-2 expression (which blocks apoptosis; its overexpression is associated with drug resistance) and counteracted the antitumor effect mediated by PYY." (PMID 37373115, 2023). "In this context, colon cancer lines counteract the antitumor effect mediated by PYY by increasing the expression of Bcl-2, which blocks apoptotic mechanisms." (PMID 37373115, 2023). "We observed that PYY transcript expression was significantly (p < 0.001) downregulated (Log2 fold change = -4.115) in aggregate colon cancer data and in all three colon cancer cohorts." (PMID 35560039, 2022). "A study reported that the highest PYY level was observed in tubular adenomatous colonic polyps; this level was lower in villous adenomatous colonic polyps, and the lowest PYY level was reported in colon carcinomas." (PMID 37373115, 2023). "Thus, low PYY levels indicate the malignant potential of these alterations, and the data show that an adenoma-carcinoma sequence occurs in colonic cancer." (PMID 37373115, 2023). "For instance, PYY is a differentially expressed, condition-specific, tissue-specific to the colon, encoded product is a secreted protein that harbors a PTM and the gene is DNA hypomethylated in a colon cancer cell line." (PMID 21352556, 2011). "PYY gene expression in human colon tumors is much reduced relative to the adjacent normal tissue; however, chemically-induced colon tumors in rats generally exhibit higher overall expression of PYY due to increased prevalence of PYY-positive cells, compared to normal mucosa." (PMID 15644144, 2005). "Cells expressing PYY were increased in an experimental animal model of colonic carcinoma, whereas no cell containing PP was observed." (PMID 37373115, 2023). "PYY stimulates proliferation of intestinal epithelium; therefore, an inhibition of PYY expression by dietary WPH may contribute to colon cancer-protective actions." (PMID 15644144, 2005). "PYY receptors have been demonstratedin colonic adenocarcinoma cell lines; however, PYY exerts no direct growth regulatory effecton colon cancer cell lines.Collectively, these findings show that it is unlikely that PYY is involved in thedevelopment and growth of colorectal carcinoma." (PMID 23292145, 2013).
malnutrition (6 papers, 2007 to 2026). Inadequate nutrition resulting from poor diet, malabsorption, or abnormal nutrient distribution. "Physiological changes affecting appetite are frequent and include appetite hormone (ghrelin, leptin, PYY, and GLP-1) effects and the subjective loss of appetite, resulting in nutritional deficiencies." (PMID 35162760, 2022). "Regression analyses identified orexin A and PYY as significant predictors of malnutrition." (PMID 41683201, 2026). "Although poor appetite is probably a major cause of malnutrition, it is mediated by a variety of factors such as age, several peptide hormones released by the gut including; ghrelin, CCK, peptide-YY, glucagon-like peptide 1, oxyntomodulin, and pancreatic polypeptide and many neurotransmitters." (PMID 30165826, 2018).
colorectal cancer (5 papers, 2013 to 2025). A primary or metastatic malignant neoplasm that affects the colon or rectum. "Research indicates that exogenous PYY can inhibit the proliferation and metastasis of colorectal cancer cells, enhancing cancer cells apoptosis." (PMID 40340969, 2025). "This may be one of the molecular mechanisms by which PYY inhibits cancer cells in colorectal cancer." (PMID 32462020, 2020). "Moreover, a low PYY expression has been observed in colorectal cancer tissue; the overexpression of this peptide promoted apoptosis in HCT116/HT29 tumor cells and blocked the proliferation, migration, and invasion of these cells, and PYY released from neurons suppressed tumor growth." (PMID 37373115, 2023). "Finally, plasma PYY level has not been related to colorectal cancer risk; however, low PYY levels indicate a malignant potential of the alterations observed in tumor cells." (PMID 37373115, 2023).
Hepatic steatosis (5 papers, 2019 to 2025). Steatosis is a term used to denote lipid accumulation within hepatocytes. "Additionally, it has influenced key metabolic regulators, including gastrointestinal hormones (e.g., GLP-1, PYY) and hepatokines (e.g., fetuin-A, selenoprotein P), in individuals with hepatic steatosis." (PMID 41228524, 2025). "Another gut-derived peptide is PYY; its secretion improves liver steatosis." (PMID 37753211, 2023).
amenorrhea (4 papers, 2012 to 2024). The absence of menses in a woman who has achieved reproductive age. "Likewise, in young female athletes with amenorrhea, the increase of PYY was negatively correlated with P1NP, which further supported the effect of PYY on bone homeostasis." (PMID 38725663, 2024). "A negative correlation between elevated PYY and P1NP in young female athletes with amenorrhea further supports an effect of PYY on bone homeostasis." (PMID 30863364, 2019).
bulimia nervosa (4 papers, 2006 to 2022). A disorder characterized by recurrent episodes of binge-eating over which the individual feels a lack of control; these episodes of binge-eating are followed by recurrent compensatory behavior to prevent weight gain, usually self-induced vomiting. "It would also be valuable to compare NPY and PYY levels across the whole spectrum of ED, including patients with bulimia nervosa and binge eating disorders." (PMID 33670342, 2021). "Status of bulimia nervosa was found to be positively correlated with plasma levels of NPY, obestatin and PYY, and negatively with leptin levels." (PMID 22681985, 2012).
carcinoid (4 papers, 2022 to 2025). "In two patients it was the carcinoid component that relapsed: one patient developed metastatic carcinoid in the breast, another patient had carcinoid recurrence in the liver associated with recrudescence of peptide YY-related constipation." (PMID 35528006, 2022). "PYY-positive carcinoids of the appendix contain almost exclusively cells expressing the peptide, whereas rectum tumors contain sporadic PYY cells." (PMID 37373115, 2023). "The involvement of peptide YY, a substance derived from carcinoid tissues known to inhibit gastrointestinal motility, might explain the constipation observed in such cases." (PMID 39980559, 2025).
colon adenocarcinoma (4 papers, 2010 to 2022). "Decreased expression of peptide YY has been reported to be relevant to the development and progression of colon adenocarcinoma." (PMID 36293321, 2022). "The decreased expression of PYY may be relevant to the development and progression of colon adenocarcinoma." (PMID 29378509, 2018).
Constipation (4 papers, 2017 to 2025). Infrequent or difficult evacuation of feces. "The results of this study indicated that the administration of loperamide to induce constipation led to significant increases in the serum PYY levels of the mice." (PMID 32974216, 2020). "Moreover, we observed that treatment with L. rhamnosus CCFM1068, FHeNJZ7-1, and FTJDG11-1 reduced the PYY concentrations in the serum of constipation model mice and alleviated the inhibitory effect of this peptide on GI transit and motility." (PMID 32974216, 2020). "Taken together, our and previous results lead us to believe that constipation could be alleviated by a probiotic intervention through decreasing the PYY levels in serum." (PMID 32974216, 2020). "It is possible that the increase in the PYY cell density in IBS-C patients would slow the intestinal transit by strengthening the ileal brake, increasing the absorption of water, and decreasing the secretion of the intestinal fluid, and thereby also result in constipation." (PMID 28764761, 2017).
Crohn disease (4 papers, 2007 to 2025). A gastrointestinal disorder characterized by chronic inflammation involving all layers of the intestinal wall, noncaseating granulomas affecting the intestinal wall and regional lymph nodes, and transmural fibrosis. "In organoids derived from patients with Crohn’s disease, PYY supplementation significantly improved epithelial regeneration, outperforming the PPAR-γ agonist rosiglitazone." (PMID 40340969, 2025). "Although elevated levels of peripheral blood PYY have been reported in Crohn’s disease patients early on, the number of PYY-positive cells in intestinal tissues shows a declining trend." (PMID 40340969, 2025). "This increase was observed one monthafter the small bowel resection and remained high throughout the six-month experiment.Circulating PYY concentrations have also been investigated in patients subjected to smallbowel resection, mainly due to Crohn’s disease." (PMID 23292145, 2013). "Similarly, elevated fasting serum PYY levels have beenreported in patients with Crohn’s disease who had previous resections of >48cm of the ileum." (PMID 23292145, 2013). "It has been shown that patients with Crohn's disease have elevated serum levels of PYY, which could be a possible explanation for upper gastrointestinal motility disturbance in these patients." (PMID 17376243, 2007). "The Crohn’s disease (CD)-like mouse model in which CD is induced by trinitrobenzene sulfonic acid (TNBS) was established and utilized to investigate this potential role for PYY 3–36." (PMID 35443853, 2022).
diarrhoea (4 papers, 2013 to 2026). "Elevated PYY is unlikely itself to be causative of the diarrhoea in BAD and IBS-D, as PYY is known to have anti-secretory and anti-propulsory activity in the colon, contrasting with pro-populsory activity of INSL5 in mice." (PMID 40701790, 2026). "Gathering the variety of pathophysiologic mechanisms resulting in diarrhoea and the important role of the ENS, we studied if OA-caused diarrhoea involves alteration of intestinal hormones (PYY) and/or neurotransmitters (5-HT and NPY)." (PMID 34148100, 2021). "We performed a set of in vivo approaches to elucidate whether neuropeptide Y (NPY), Peptide YY (PYY) or serotonin (5-HT) was implicated in the early OA-induced diarrhoea." (PMID 34148100, 2021). "In our study, several participants reported diarrhoea during the antibiotic course, and after completion of the course, plasma PYY concentrations were increased." (PMID 26562532, 2015). "Administration of PYY inhibits diarrhoea in experimental animals by reducing intestinal fluid secretion and slowing colon transit." (PMID 24073715, 2013). "Increased secretion of PYY has previously been reported in patients with diarrhoea following gastrointestinal infection and an important function of PYY may be to limit nutrient and water excretion by reducing colonic transit time and fluid secretion." (PMID 26562532, 2015). "PYY inhibited Prostaglandin E2 (PGE2) and Vasoactive Intestinal Peptide that stimulated intestinal water secretion in the human small intestine being a defence against diarrhoea." (PMID 34148100, 2021).